SS18 (SS18 subunit of BAF chromatin remodeling complex)
Diseases named in the same sentence as SS18 in open-access papers (continued):
Sharing a sentence is not in itself a finding about the gene and the disease.
cancer (34 papers, 2010 to 2026). A tumor composed of atypical neoplastic, often pleomorphic cells that invade other tissues. "We show that treatment with CBP/p300 dual inhibitors causes synthetic lethality in cBAF-deficient cancers such as SMARCA4/SMARCA2-deficient and SS18–SSX fusion cancers." (PMID 39625239, 2025). "As SS18 is a known member of two types of mammalian SWI/SNF (BAF) chromatin remodeling complexes—mutations in which contribute to over 20% of all human cancers – its involvement in diverse cancer types is both significant and biologically plausible." (PMID 40849585, 2025). "Furthermore, treatment with CBP/p300 dual inhibitor suppressed the growth of xenografts derived from SMARCA4/SMARCA2-deficient and SS18–SSX fusion cancer cells, resulting from repression of KREMEN2 and induction of apoptosis." (PMID 39625239, 2025). "Thus, simultaneous suppression of CREBBP and EP300, but not that of either alone, causes synthetic lethality in SMARCA4/SMARCA2-deficient and SS18–SSX fusion cancers." (PMID 39625239, 2025). "Thus, SMARCA4/SMARCA2-deficient and SS18–SSX fusion cancer cells depend on the expression of KREMEN2." (PMID 39625239, 2025). "To further confirm that KREMEN2 is a determinant of synthetic lethality through simultaneous inhibition of CBP/p300 in SMARCA4/SMARCA2-deficient cells and SS18–SSX fusion cancer cells, we investigated whether depleting KREMEN2 affects cell viability." (PMID 39625239, 2025). "Because SMARCA4/SMARCA2-deficient and SS18–SSX fusion cancer cells depend on transcriptional upregulation of KREMEN2 due to SMARCA4/SMARCA2 deficiency and SS18–SSX fusion, we clarified that synthetic lethality is induced by repressing expression of KREMEN2 by simultaneous inhibition of CBP/p300." (PMID 39625239, 2025). "Therefore, this study examined the potential for expansion and adaptation of simultaneous CBP/p300 inhibitors for use against cancers with SS18–SSX fusion and the majority of SMARCA4/SMARCA2-deficient in addition to SMARCB1 deficient, which was reported previously." (PMID 39625239, 2025). "On the other hand, the sensitivity of ARID1A-deficient cancer cell lines to CBP/p300 dual inhibitors was intermediate between SWI/SNF WTs and the sensitive genotypes (SMARCA4/SMARCA2-deficient and SS18–SSX fusion)." (PMID 39625239, 2025). "Constituent genes (e.g., SMARCB1, SMARCA4, SMARCA2, and SS18) of the SWI/SNF complex often harbor genetic abnormalities in various cancers." (PMID 39625239, 2025). "Previous studies have determined a direct role for the SS18-SSX fusion protein in regulating expression of several cancer-related genes, such as EGR1, FOS, IGF2, FZD10, SOX2, UNCX and CDH4." (PMID 39045458, 2024). "Our case is the first report of a non‐SS malignant neoplasm identified in the literature to harbor the novel SS18::NEDD4 fusion gene." (PMID 35639915, 2022). "A combination of cell-based and biochemical approaches reveals how oncogenic fusion protein SS18-SSX directs BAF complexes to H2AK119Ub-modified nucleosomes to remodel chromatin at cancer-specific gene targets." (PMID 32747783, 2020). "As the sole driving cytogenic event, t(X;18) generates the SS18-SSX protein complex that leads to the distinct phenotype of this cancer and provides an attractive target for drug intervention." (PMID 28056055, 2017). "In this study, we show that simultaneous inhibition of a paralog pair (CBP and p300) causes synthetic lethality in SMARCA4/SMARCA2-deficient cancer cells and SS18–SSX fusion cancer cells; these results are similar to those obtained for SMARCB1-deficient cancer cells." (PMID 39625239, 2025). "Per AACR GENIE, SS18 amplification is present in 0.16% of carcinoma cases, mostly adenocarcinomas." (PMID 40416104, 2025). "In the GSEA analysis, SS18 was shown to be associated with nuclear division and cell adhesion molecules indicating that SS18 might promote proliferation and metastasis of cancer cells." (PMID 36531058, 2022).
cancer (continued). "However, deletion of SS18 has also been reported in a small subset (0.14%) of cancers." (PMID 38654044, 2024). "The SS18::SSX fusion protein interacts with the SWI/SNF (BAF) complex, a large, chromatin modifying complex dysregulated in many human cancers." (PMID 40804185, 2025). "SS18 participates in BAF complexes that open chromatin, while the SSX genes are cancer-testis antigens that interface with chromatin decorated with monoubiquitinated histone H2A placed by polycomb repressive complex activity." (PMID 40299558, 2025). "The aberrations of SMARCB1, SMARCA4, ARID1A, PBRM1, and SS18 within the SWI/SNF complex are frequently found in rare cancers and refractory cancers." (PMID 39625239, 2025). "Although there is not any reports of MEF2C::SS18L1 in hematologic tumors at present, the presence of recurrent MEF2C::SS18 fusions in MSA suggests the importance and specificity of this fusion in pathogenesis of malignant tumor." (PMID 38907739, 2024). "BRD9 is frequently amplified in cancer and is a vulnerability in cancer cells with inactivation of SMARCB1 or tumors having an oncogenic SS18-SSX fusion." (PMID 35323214, 2022). "We demonstrate here that the paralogous cancer-related minor SWI/SNF subunits DPF1, -2, -3; BCL7A, -B, -C; and SS18 and SS18L1 reside in BAF-class human SWI/SNF complexes and, that PHF10 marks PBAF SWI/SNF complexes." (PMID 22442726, 2012). "While FYN is known to promote cellular proliferation and migration in multiple types of cancer, our findings reveal that SS18-SSX exerts a negative effect on FYN expression, at least in part, by repressing FYN transcription." (PMID 39045458, 2024). "The main driving genetic event in this cancer is known, yet no means to target the fusion protein SS18-SSX directly exists." (PMID 30909651, 2019). "Interestingly, the SS18-SSX fusion genes are expressed in >95% of SS and appear to directly contribute to the cancer phenotype." (PMID 20981248, 2010). "Although the mechanisms by which the novel SS18::NEDD4 gene fusion have not been fully elucidated, individual perturbations in SS18‐ and NEDD4‐mediated signaling pathways are recognized for promoting human cancer and tumorigenesis." (PMID 35639915, 2022).
adenocarcinoma (3 papers, 2024 to 2025). A common cancer characterized by the presence of malignant glandular cells. "MSA was previously grouped as “adenocarcinoma, not otherwise specified” (NOS) and classified as a unique pathologic entity by recognition of recurrent MEF2C::SS18 fusion." (PMID 38982505, 2024).
infection (1 paper, 2023). The state of being infected such as from the introduction of a foreign agent such as serum, vaccine, antigenic substance or organism. "Plants of variety LC05-136 can also be induced to form black whips from the top of plant stalks, but not induce flowers after infection by the mixture of Ssf1-7 + Ss18 or Ssf1-8 + Ss17 (data not showed)." (PMID 36679029, 2023).
SS18 also shares sentences with these, for which no sentence is quoted: alveolar rhabdomyosarcoma (8 papers); liposarcoma (4); gastrointestinal stromal tumor (2); osteosarcoma (2); prostate carcinoma (2); bone tumors (1); breast carcinoma (1); chondrosarcoma (1); chronic myelogenous leukemia (1); desmoid tumor (1); desmoplastic small round cell tumor (1); endometrial stromal sarcomas (1); Head and Neck Tumour (1); hematologic tumors (1); leiomyosarcoma (1); malignant mesothelioma (1); malignant peripheral nerve sheath tumor (1); medulloblastoma (1); neuroendocrine carcinoma (1); NUT carcinoma (1); ovarian small cell carcinoma (1); pancreatic tumor (1); rhabdoid tumor (1); salivary duct carcinoma (1); salivary gland neoplasm (1); solitary fibrous tumor (1); spindle cell rhabdomyosarcoma (1); spindle cell sarcoma (1); supratentorial ependymoma (1); thoracic tumor (1).